LINC01963 (long independently transcribed non-coding RNA 1963)
Synonyms: DKFZp434H1419; PKI55
Gene: Long non-coding RNA gene on chromosome 2 (216,217,045 to 216,246,041, forward strand). Ensembl gene ENSG00000260804.
Diseases named in the same sentence as LINC01963 in open-access papers:
LINC01963 is named in the same sentence as 7 diseases in open-access papers, as found by Europe PMC text mining. Sharing a sentence is not in itself a finding about the gene and the disease. The quoted sentences say what the papers report.
pancreatic carcinoma (5 papers, 2021 to 2023). "Previous studies have shown that LINC01963 expression which is lower in pancreatic carcinoma and oral and oropharyngeal squamous cell carcinoma tissues plays an oncogenic role and acts as a marker of poor prognosis." (PMID 35152275, 2022). "Consistent with our study, the outcomes in these studies supported the multiple functions of LINC01963 in a variety of carcinomas, including pancreatic carcinoma, ccRCC, and OSCC/OPSCC." (PMID 35538487, 2022). "LncRNA LINC01963 represses pancreatic carcinoma progression via regulating miR-641/TMEFF2 axis." (PMID 38006396, 2023). "In addition, LINC01963 negatively regulates the expression of microRNA-641 and inhibits the progression of pancreatic cancer." (PMID 36406148, 2022). "LINC01963 is expressed at lower levels in pancreatic cancer tissues and cell lines." (PMID 36406148, 2022). "Thus, LINC01963 suppresses the progression of pancreatic cancer through the miR-641/TMEFF2 axis." (PMID 34827663, 2021). "We also identified that the low expression of MEG3, LINC01963, and LINC00261 and the high expression of MACC1-AS1, LINC00462, LINC01559, and UCA1 were significantly correlated with worse survival in pancreatic cancer patients." (PMID 34827663, 2021). "The lncRNA LINC01963 has been confirmed to be significantly lower in pancreatic carcinoma tissues and cell lines by targeting miR-641/TMEFF2, whereas silence of LINC01963 could improve the development of cell culture tumors." (PMID 35538487, 2022). "LINC01111/miR-3924, LINC01963/miR-641, DGCR5/miR-27a-3p, GAS5/miR-32-5p, and LINC00261/miR-23a-3p axes are examples of the latter type of lncRNA/miRNA interactions in the context of pancreatic cancer." (PMID 34827663, 2021).
prostate carcinoma (1 paper, 2022). A carcinoma that arises from epithelial cells of the prostate gland. "We found that LINC01963 silencing enhanced the chemosensitivity of PC3-DR cells to DTX, indicating that LINC01963 is a potential therapeutic target for treating patients with prostate cancer with DTX resistance." (PMID 35152275, 2022).
tumor (2 papers, 2021 to 2026). "On the other hand, LINC01111, LINC01963, DGCR5, MEG3, GAS5, and LINC00261 are among tumor suppressor lncRNAs in this tissue." (PMID 34827663, 2021). "Furthermore, high LINC01963 expression was correlated with poor PDAC prognosis, and functional studies demonstrated that its knockdown inhibited PDAC cell proliferation and xenograft tumor growth." (PMID 41639735, 2026).
carcinoma (1 paper, 2022). A malignant tumor arising from epithelial cells. "Importantly, lncRNA LINC01963 may play a crucial role in various carcinomas." (PMID 35538487, 2022).
infection (1 paper, 2022). The state of being infected such as from the introduction of a foreign agent such as serum, vaccine, antigenic substance or organism. "Compared with NC group, LINC01963 expression was significantly upregulated in PC3 cells after infection with ov-LINC01963 lentivirus, while it was significantly downregulated in PC3 cells after infection with sh-LINC01963-2 lentivirus." (PMID 35152275, 2022). "Compared with NC group, LINC01963 expression was significantly upregulated after infection with ov-LINC01963 lentivirus, while it was significantly downregulated after infection with sh-LINC01963-2 lentivirus in PC3-DR cells." (PMID 35152275, 2022).
LINC01963 also shares sentences with these, for which no sentence is quoted: oropharyngeal squamous cell carcinoma (1 paper); pancreatic ductal adenocarcinoma (1).